MCM7 (minichromosome maintenance complex component 7)
Diseases named in the same sentence as MCM7 in open-access papers (continued):
Sharing a sentence is not in itself a finding about the gene and the disease.
cancer (continued). "For instance, MCM7, a marker of a high proliferation rate in cancer, is upregulated in B-ALL EVs." (PMID 38023151, 2023). "In contrast, knockout of MCM7 activates checkpoint signaling in human cancer cells, prohibiting their unbitted DNA replication, which may act as the potential target for cancer treatment." (PMID 36776764, 2023). "MCM7 is regarded as an extensive mark for cancer development." (PMID 36776764, 2023). "An integrative protein-drug interaction, molecular docking, ADMET, QM calculation, MD simulation, and MM-GBSA approaches revealed CID_387447 and CID_3062316, as potential drug candidates that will help to inhibit the activity of the MCM7 protein against human cancer." (PMID 35087187, 2022). "Therefore, we can conclude that the compounds dasatinib and bortezomib can inhibit the activity of the MCM7 and can be developed as a treatment option against human cancer." (PMID 35087187, 2022). "In addition to MCM2 to MCM7, six downstream oncogenic targets of c-MYC implicated in cancer survival and metabolism including PSMA1, PSMA6, PSMB2, HDAC2, LDHA and SPRING were positively correlated with IFITM3 in 71 GC specimens using the Cho dataset." (PMID 35941699, 2022). "However, the study aimed to identify potential small molecular drug candidates against the MCM7 protein that can utilize treatment options for human cancer." (PMID 35087187, 2022). "In addition, it has been demonstrated that MCM7 promotes cancer progression through cyclin D1-dependent signaling." (PMID 35386284, 2022). "A previous study showed that the high expression of MCM2, MCM5, and MCM7 might indicate a poor prognosis of cancer." (PMID 34413873, 2021). "There is currently no effective agent that can prevent the development of cancer caused by the MCM7 protein." (PMID 34641424, 2021). "The researchers concluded that high expression of MCM2, MCM5, and MCM7 might be prognostic indicators for poor outcomes in cancers." (PMID 32089988, 2020). "High expression of MCM7 can serve as a predictive biomarker for poor prognosis in human cancers." (PMID 31640696, 2019). "RNA sequencing also showed that MCM7 was overexpressed in multiple cancer tissues." (PMID 31186405, 2019). "Moreover, reducing MCM7 expression in cells with high basal expression led to decreased cell proliferation, showing the dependence of cancer cells on this alteration." (PMID 31308377, 2019). "Phosphosites of MCM7 and the signaling pathways involved may affect the role of MCM7 phosphorylation in cancer development." (PMID 30062004, 2018). "Potentiation of Mcm7 phosphorylation has been observed in several cancers." (PMID 29651420, 2018). "Recent studies have demonstrated that MCM7 is a potential therapeutic target in several cancers." (PMID 28465488, 2017). "Although the positive immunostaining of MCM7 in cancer has been frequently observed, the oncogenic role of MCM7 in cancer development remains unclear." (PMID 28182015, 2017). "Taken together, our results suggest that MCM7–cyclin D1 pathway may participate in cancer progression and serve as a biomarker for prognosis in HCC." (PMID 28182015, 2017). "In addition to the genes related to the immune system, our findings also demonstrated that treatment with Cy down-regulates the expression of several genes (e.g., Ras, LMO2, MCM4 and MCM7) that are related to cancer development and cell cycle progression." (PMID 24466173, 2014). "The drug may also have in vivo utility against Mcm2-7 as it has been shown to selectively decrease the proliferation of cancer cells overexpressing Mcm7 in tissue culture." (PMID 25243149, 2014). "From this point of view, increased level of MCM7 at early time interval after anti-cancer DOXO treatment may reflect other adaptive mechanisms of cancer cell contributing to the transformation of cell." (PMID 23443080, 2012).
cancer (continued). "The cell viability analysis revealed that MCM7 siRNAs had only slight effects on these normal cell lines relative to cancer cell lines, implying that the marked suppression of cancer cell growth by treatment with these specific siRNAs was not dependent on off-target effects." (PMID 21619671, 2011). "This kind of evidence also reinforces the importance of MCM7 as a target for cancer therapy." (PMID 21619671, 2011). "Therefore, we should take this kind of evidence into consideration when developing anti-cancer therapy targeting MCM7." (PMID 21619671, 2011). "We hypothesized that MCM7 levels in ccRCC are dysregulated and impact cancer progression." (PMID 40943553, 2025). "Also, MCM7 is among the known biomarkers for cancer development that are targets for therapies." (PMID 39801521, 2025). "The miR-107/MCM7/PAK2 pathway may therefore contribute to the development of cancer." (PMID 39769207, 2024). "However, on the molecular level, inhibiting MCM7 lowers cancer-related cellular growth." (PMID 34641424, 2021). "Previous studies suggested that MCM7 SNPs could be used as prognostic markers for cancer." (PMID 31936215, 2020). "In order to examine whether elevated expression of MCM7 plays a critical role in the proliferation of cancer cells, we prepared siRNA oligonucleotide duplexes to specifically suppress the expression of MCM7 (siMCM7#1, #2), and transfected each of them into cancer cells." (PMID 21619671, 2011). "Importantly, specific MCM7 signals were hardly detected in normal brain, heart, lung, liver, pancreas, stomach, testis, kidney and bladder tissues, indicating that MCM7 may be specifically overexpressed in cancer tissues." (PMID 21619671, 2011). "In this study, we show for the first time that the MCM7 protein is upregulated in RCC and confirm its role in cancer proliferation." (PMID 40943553, 2025). "We demonstrate that MCM7 is upregulated at both transcript and protein levels in RCC, contributing to cancer progression by regulating cell proliferation and caspase-3/7 activity." (PMID 40943553, 2025). "Furthermore, certain cell cycle–related proteins, including TOP2A, PCNA, MCM2, MCM4, MCM5, MCM6, and MCM7, have also been reported to facilitate cancer cell proliferation, and the enhanced expression of these cell cycle–related proteins may contribute to uncontrolled ESCC cell proliferation." (PMID 38652547, 2024). "We found that in the case of the ALT high TEL high phenotype, genes TRIP13, TPX2, and MCM7 were upregulated in eight cancer types and ADAMTS8 in seven cancer types was downregulated." (PMID 38763334, 2024). "MCM7 phosphorylation (Y600) through the epidermal growth factor/Lyn kinase cascade enhances MCM complex assembly and cancer cell proliferation." (PMID 37517032, 2023). "We verified the four up-regulated lncRNAs (TCONS_00020615, TCONS_00055555, TCONS_00106091, and TCONS_00130858) and eight cancer-related mRNAs (CDCA3, DIAPH3, MCM7, NCAPG2, TPD52, PRC1, SETD6, and KIF22) involved in the ceRNA network by qRT-PCR." (PMID 37098483, 2023). "Minichromosome maintenance complex component 7 (MCM7) and cyclin dependent kinase 6 (CDK6) are classical cancer-related genes that are essential for genome replication and regulating the cell cycle, respectively." (PMID 37005685, 2023). "In the 7q21–22 area of the GC chromosome, numerous genes, including SHFM1, MCM7, and COL1A2, have been identified as likely cancer candidate genes." (PMID 37594635, 2023). "Recent studies revealed that PRMT5 physically interacts with MCM7 in HCT8 cells, while MCM7 depletion impairs cancer cell migration and invasion." (PMID 36776764, 2023). "The phosphorylation of MCM7 at Tyr-Y600 by EGFR, which promotes the proliferation of cancer cells, facilitates the creation and loading of the MCM complex." (PMID 37594635, 2023). "MCM6, MCM7, and MCM8 collaborate with other MCM family members to promote cancer cell proliferation through cell cycle and DNA replication." (PMID 35360518, 2022).
cancer (continued). "In summary, expression profiling of 2 human cancer cell lines identified several components of the PI3K/AKT pathway and the MMP inhibitor TIMP2 as candidate MCM7 targets." (PMID 35192608, 2022). "The distributions of Ki67 and MCM7 in each lesion demonstrated that high expression levels were present in HGD and in carcinomas." (PMID 36061145, 2022). "Phosphorylation of MCM7 mediated by EGFR-p56Lyn and RACK1-Akt promotes MCM complex assembly and chromatin loading, therefore enhancing DNA synthesis and cancer cell proliferation." (PMID 30062004, 2018). "Most of the miR-22-regulated targets involved in carcinoma development pathway were recently validated, including MYCBP, MCM7, CDC25C, and CCNA2, all of which are responsible for the cell proliferation." (PMID 27738335, 2016). "Two nodes, named Mcm4 and Mcm7, were upregulated in AD vs. K and in AD vs. D. These findings suggested that any gene expression level changes in module 1 could result in the dysregulation of cell cycle progression and could affect the progression of inflammation and cancer." (PMID 24743346, 2014). "We selected the overlapped genes-PLK1, MCM2, MCM3, MCM7, MCM10 (ranked 13 by NGP-NR in NSCLC patient datasets) and SKP2 to investigate their functions in cancer." (PMID 22838965, 2012). "The cellular protein MCM7, a helicase involved in DNA replication, is induced by HPV-E7 expression in clinical samples of CIN and carcinoma lesions." (PMID 22911850, 2012). "To date, MCM7 has been investigated almost solely in cancer, and there is a lack of research on its role in degenerative diseases." (PMID 35332256, 2022). "In addition, H2AFX, MCM2, MCM7, and POLD1 were highly up-regulated in 31 cancer tissues, based on the analysis of TCGA data." (PMID 33442399, 2021). "In summary, the data show a vulnerability of KRAS-mutant cells towards suppression of MCM7 and suggest that inhibiting DNA replication licensing might be a viable strategy to target KRAS-mutant cancers." (PMID 32612138, 2020). "MCM7 phosphorylation at Tyr-600 mediated by epidermal growth factor receptor (EGFR)-p56Lyn-axis promotes MCM complex assembly and chromatin loading, consequently enhancing DNA synthesis and cancer cell proliferation." (PMID 30062004, 2018). "MCM4 and MCM7 are the part of MCM protein family, which play an essential roles in initiation of DNA replication and may be pre-cancer markers." (PMID 26156831, 2015). "Expression analysis of post-differentiation mixed-populations indicates reduced transcripts of the ABC-transporter and cancer stemness marker ABCG2 and higher expression of cell proliferation marker minichromosome maintenance 7 (MCM7) compared to undifferentiated SP-fractions." (PMID 22768203, 2012). "To clarify detailed functions of PRMT6 in cancer, we performed IP-MS analysis and identified MCM7 as a binding partner (data not shown)." (PMID 21619671, 2011). "In this study, we demonstrate that dysregulation of MCM7 expression is observed in various types of cancer and correlates with a negative outcome in patients with NSCLC after surgical resection." (PMID 21619671, 2011). "On top of that, it has been suggested that MCM7, a significant subunit of the assumed heteromeric MCM helicase, has a role in the development and spread of tumors and may be a biomarker for a number of human cancers." (PMID 39769207, 2024). "Additionally, HDAC2, MCM7, and PTTG1 have also shown potential for treating cancers." (PMID 38001498, 2023). "Besides, H2AFX, MCM2, MCM7, and POLD1 were highly up-regulated in 31 cancer tissues." (PMID 33442399, 2021). "Numerous studies suggest that phosphorylation of MCM7 is directly correlated with its binding to chromatin and other MCM family members, and decreases in this binding inhibit the helicase activity of MCM7, DNA replication, S-phase entry, and cancer cell growth." (PMID 28465488, 2017). "Our new findings indicate that MCM7 may be an ideal target for molecular targeted therapy of cancer without severe side effects." (PMID 21619671, 2011).
cancer (continued). "However, in Bi-L E7/K14-tTA/FancD2−/− mice treated with doxycycline, expression of MCM7 was restricted in its expression to the poorly differentiated cells not only within the epithelium but also in the cancers, confirming that E7 is no longer expressed in those cancers." (PMID 27190216, 2016). "Our results suggest that the top-ranked genes by NGP-PLK1, MCM2, MCM3, MCM7, MCM10 and SKP2 might coordinate to promote cell cycle related processes in cancer but not normal cells." (PMID 22838965, 2012). "The top-ranked genes by NGP-PLK1, MCM2, MCM3, MCM7, MCM10 and SKP2 might coordinate to promote cell cycle related processes in cancer but not normal cells." (PMID 22838965, 2012).
infection (6 papers, 2009 to 2025). The state of being infected such as from the introduction of a foreign agent such as serum, vaccine, antigenic substance or organism. "The E7K81S mutant-induced lesions showed evidence of increased expression of MCM7 and suprabasal DNA synthesis, similar to lesions caused by wild type MmuPV1 infection." (PMID 37036883, 2023). "The knockdown of MCM7 decreased the expression of the MVC protein significantly and suppressed MVC replication by arresting the cell cycle in the G0/G1 phase during infection." (PMID 41011485, 2025). "In this study, we have used siRNA knockdowns of Cdc6, Cdt1, ORC2 and MCM7 to address their role, if any, in HCMV DNA replication and show that infection of cells depleted for these proteins results in enhanced viral lytic DNA replication." (PMID 22586460, 2012). "The knockdown of MCM7 decreased the expression of this MVC protein significantly, as well as suppressing MVC replication by arresting the cell cycle in the G0/G1 phase during infection." (PMID 41011485, 2025). "However, unlike our previous results with Ad-DN-infected CASMCs, Ad-DN infection of PPARγ−/− ES did not induce cyclin A, MCM7, or pRb expression versus Ad-GFP-infected cells under either serum-starvation or -stimulation conditions." (PMID 20300579, 2009). "Hence, the mechanisms by which EcPV2 infection promotes MCM7 expression by non-basal cells remains unclear." (PMID 31640696, 2019).
adenocarcinoma (5 papers, 2011 to 2021). A common cancer characterized by the presence of malignant glandular cells. "An investigative comparison of Ki67 vs. Mcm7 immunohistochemistry staining was conducted and demonstrated that Mcm7 correlated highly with Ki67, but demonstrated an improved ability to distinguish between benign, PIN and adenocarcinoma." (PMID 22641253, 2012).
prostate (3 papers, 2012 to 2021). "However, over-expression of MCM7 along with a PTEN-targeting microRNA cluster encoded within the MCM7 human locus did initiate prostate tumorigenesis." (PMID 23133403, 2012).
MCM7 also shares sentences with these, for which no sentence is quoted: esophageal squamous cell carcinoma (3 papers); Barrett esophagus (2); dysplasia (2); endometrial carcinoma (2); Insulin resistance (2); oral squamous cell carcinoma (2); penile tumor (2); bladder tumor (1); breast tumor (1); bronchioloalveolar carcinoma (1); chondrosarcoma (1); colorectal adenocarcinoma (1); Cornelia de Lange syndrome (1); COVID-19 (1); diabetic nephropathy (1); DiGeorge syndrome (1); endometrial endometrioid adenocarcinoma (1); endometrial mixed adenocarcinoma (1); endometrial serous adenocarcinoma (1); Fanconi anemia (1); gastrointestinal stromal tumor (1); gynecological cancer (1); head and neck squamous cell carcinoma (1); Hodgkins lymphoma (1); hyperthyroidism (1); hypothyroidism (1); intervertebral disc degeneration (1); larynx (1); leiomyoma (1); lung squamous cell carcinoma (1).
A further 17 diseases each share a sentence with MCM7 in 1 paper.